SSH3 (slingshot protein phosphatase 3)
Description:
Protein phosphatase which may play a role in the regulation of actin filament dynamics. Can dephosphorylate and activate the actin binding/depolymerizing factor cofilin, which subsequently binds to actin filaments and stimulates their disassembly (By similarity).
Synonyms: SSH3L; FLJ20515; FLJ10928
Tractability: Antibody: the Human Protein Atlas places it where antibodies can reach. PROTAC: ubiquitination databases record sites on it; its protein half-life has been measured.
Gene: Protein-coding gene on chromosome 11 (67,303,478 to 67,312,607, forward strand). Ensembl gene ENSG00000172830.
Subcellular location: Cytoplasm, cytoskeleton; Nucleus
Subcellular location (Human Protein Atlas): Cytosol; Nuclear speckles; Actin filaments; Plasma membrane
Gene Ontology:
Molecular function: protein binding; actin binding; phosphoprotein phosphatase activity; phosphatase activity; protein serine/threonine phosphatase activity; protein tyrosine phosphatase activity
Biological process: actin cytoskeleton organization; negative regulation of actin filament polymerization
Cellular component: cytoplasm; cytoskeleton; nucleus
Genetic constraint (gnomAD): Loss-of-function variants: 67 observed, 76.82 expected, observed/expected ratio (o/e) 0.87, 90% interval 0.71 to 1.07. The upper end of that interval is the gene's LOEUF score, 1.07, which puts it in group 4 of 6, group 1 being the genes least tolerant of losing a copy. Missense variants: 824 observed, 892.8 expected, observed/expected ratio (o/e) 0.92, 90% interval 0.87 to 0.98. Synonymous variants: 318 observed, 358.84 expected, observed/expected ratio (o/e) 0.89, 90% interval 0.81 to 0.97.
Homologues: Orthologues: chimpanzee SSH3 (99% identical), macaque SSH3 (95% identical), dog SSH3 (83% identical), guinea pig SSH3 (81% identical), rat Ssh3 (81% identical), mouse Ssh3 (80% identical), rabbit SSH3 (72% identical), pig SSH3 (69% identical), tropical clawed frog ssh3 (42% identical), zebrafish si:ch211-203d1.3 (39% identical). Paralogues in human: SSH1 (38% identical), SSH2 (38% identical), DUSP16 (15% identical), DUSP8 (15% identical), STYXL2 (15% identical), DUSP7 (14% identical), DUSP9 (14% identical), DUSP6 (14% identical), DUSP10 (13% identical), DUSP4 (13% identical), DUSP1 (12% identical), DUSP5 (12% identical), and 19 more.
Diseases named in the same sentence as SSH3 in open-access papers:
SSH3 is named in the same sentence as 3 diseases in open-access papers, as found by Europe PMC text mining. Sharing a sentence is not in itself a finding about the gene and the disease. The quoted sentences say what the papers report.
colorectal cancer (2 papers, 2022 to 2024). A primary or metastatic malignant neoplasm that affects the colon or rectum. "Of note, SSH-family gene expression, mainly SSH1 (Spearman correlation; P = 0.0201) and SSH3 (Spearman correlation; P = 0.0200), was positively and significantly correlated to paladin gene expression in pan-cancer TCGA colorectal cancer patients." (PMID 35882839, 2022). "SDHAF1 plays a crucial role in linking the citric acid cycle and electron transport chain, while SSH3 has been identified as a potential antigen for developing mRNA-based vaccines against balder urothelial carcinoma (BLCA) and has been associated with colorectal cancer cell invasion and metastasis." (PMID 39161762, 2024).
cancer (3 papers, 2012 to 2022). A tumor composed of atypical neoplastic, often pleomorphic cells that invade other tissues. "Other genes down-regulated by rosiglitazone belonged mainly to two functional groups: “cancer” (RPS27A, SORBS2, STIP1, FGA, FGFR2, SSH3, EPN1) and cell death (SORBS2, STIP1, GAS2, EPN1)." (PMID 22761953, 2012). "However, some of the members participate in the promotion of cancer development, such as STYX, SSH1, and SSH3." (PMID 33053837, 2020).
tumor (1 paper, 2023). "Six upregulated and mutated tumor antigens related to NMD, and infiltration of APCs were identified in patients with BLCA, including HP1BP3, OSBPL9, SSH3, ZCCHC8, FANCI, and EIF4A2." (PMID 36761744, 2023). "Six tumor antigens (HP1BP3, OSBPL9, SSH3, ZCCHC8, FANCI and EIF4A2) were correlated with the expression of NMD factors and infiltration of APCs, which may be promising candidates for mRNA vaccines." (PMID 36761744, 2023).